CAT (catalase)
Diseases named in the same sentence as CAT in open-access papers (continued):
Sharing a sentence is not in itself a finding about the gene and the disease.
Hyperammonemia (4 papers, 2017 to 2024). An increased concentration of ammonia in the blood. "Previously, a study reported that hyperammonemia leads to a decrease in the activities of GPx, catalase and SOD and increases the formation of superoxide in the brains of rats." (PMID 37371422, 2023). "The action of citrulline on catalase activity, as well as on some other antioxidant enzymes, arises from the results of a previous study showing the inhibitory action of citrullinemia and hyperammonemia." (PMID 38256015, 2024). "Similarly, hyperammonemia was associated with significant decline in the activity of SOD (P < 0.01), CAT (P < 0.01), and GPx (P < 0.001) in the liver of rats." (PMID 28744340, 2017). "For example, in one study of animals with induced hyperammonemia, MCE administration increased superoxide dismutase and catalase activity, inhibiting and improving oxidation." (PMID 32587872, 2020).
hyperhomocysteinemia (4 papers, 2017 to 2024). A serious metabolic condition caused by mutations in the MTHFR gene, medications, or nutritional deficiency. "Subchronic treadmill training in the rats with hyperhomocysteinemia triggers the colon tissue antioxidant response (by increasing the activities of superoxide dismutase and catalase) and elicits an increase in metabolic enzyme activities (lactate dehydrogenase and malate dehydrogenase)." (PMID 38396625, 2024). "The redox imbalance is probably not directly related to hyperhomocysteinemia and is hypothetically caused by other pathological processes or by an indirect effect of Hcy, for example, on the enzymatic antioxidant defence system (CAT activity), which requires further exploration." (PMID 34707909, 2021). "However, this is unlikely in our model because we have demonstrated previously that diet-induced hyperhomocysteinemia in mice does not influence tissue levels of catalase, glutathione peroxidase, or other isoforms of SOD." (PMID 28414812, 2017).
Hyperinsulinemia (4 papers, 2015 to 2025). An increased concentration of insulin in the blood. "Hyperinsulinemia is linked to lower albumin, albumin/globulin ratio, catalase activity, glucose, and glucose/insulin ratio." (PMID 40901060, 2025). "CAT activity (p = 0.004) and NO (p = 0.0001) levels were maximum in mares with normal insulin-light BW and were minimum in hyperinsulinemia-light mares." (PMID 40901060, 2025).
Hypoglycemia (4 papers, 2012 to 2024). A decreased concentration of glucose in the blood. "Hypoglycemia is associated with decreased activity of the antioxidant enzymes catalase and super oxide dismutase." (PMID 23894333, 2013). "Despite the decrease in catalase activity in the brain, the total antioxidant capacity following severe insulin-induced hypoglycemia increased." (PMID 39004753, 2024). "In the current research, it was observed that after repeated episodes of insulin-induced severe hypoglycemia in rats, there was a significant decrease in the brain tissue level of catalase." (PMID 39004753, 2024). "During hypoglycemic clamps, intracerebroventricular catalase increased glucagon and epinephrine responses to hypoglycemia, consistent with perceived lower glucose levels." (PMID 27740870, 2016). "As well, low expression levels of genes protective against oxidative stress or hypoglycemia/hypoxia insult, such as catalase or hypoglycemia/hypoxia inducible mitochondrial protein 1, are implicated in the susceptibility of β-cells to stress." (PMID 22509386, 2012). "In keeping with our hypothesis that reduced H2O2 levels in the brain would be interpreted as reduced blood glucose levels, ICV infusion of catalase significantly increased the adrenaline produced as part of the counterregulatory response to hypoglycemia at plasma glucose levels of 3.5mM and 2.5mM." (PMID 27740870, 2016). "To examine the contribution of H2O2 signaling to the control of counterregulatory responses to hypoglycemia, we performed hyperinsulinemic hypoglycemic clamps in rats receiving ICV catalase." (PMID 27740870, 2016). "Similarly, glucagon responses to hypoglycemia were amplified and peaked at a higher plasma glucose level in the group receiving ICV catalase, consistent with a shifted threshold for counterregulatory responses in this group." (PMID 27740870, 2016).
infarction (4 papers, 2014 to 2025). A localised pathological necrosis of tissue resulting from obstruction of the blood supply usually by a thrombus, an embolus, or vascular torsion. "Long-term and moderate exercise (75% of VO2max for 6 weeks) before infarction injury has also been shown to increase FOXO3 and its two downstream targets, MnSOD, and catalase, compared to sedentary rats with infarction." (PMID 36036015, 2022). "On the other hand, we observed an increase in catalase (CAT) and glutathione peroxidase (GPx) activities in post-infarction subjects in comparison to controls, for smokers and non-smokers (p < 0.05)." (PMID 25257356, 2014). "Furthermore, post-infarction patients had elevated hs-CRP, MDA, CAT and GPx levels compared to controls for both smokers and non-smokers." (PMID 25257356, 2014).
ischemia reperfusion injury (4 papers, 2012 to 2023). Adverse functional, metabolic, or structural changes in ischemic tissues resulting from the restoration of blood flow to the tissue (reperfusion), including swelling; hemorrhage; necrosis; and damage from free radicals. "An enzyme complex [containing polyhemoglobin, SOD, catalase and carbonic anhydrase (PolyHb-SOD-CAT-CA)] has been developed as a blood-substitute also acting as an antioxidant and therapeutic agent against ischemia-reperfusion injuries." (PMID 34458243, 2021). "Dong X et al15 confirmed the difference in the expression of oxidative stress indicators such as superoxide dismutase, catalase, glutathione, malon-dialdehyde, and oxidized protein in muscle specimens of ischemia-reperfusion injury model rats that received 25 μg/kg dexmedetomidine." (PMID 37250551, 2023). "Supplementation with Ori reduced the levels of SOD2, CAT, MDA, ROS levels, and IL-1β, TNF-α in hind limb muscle tissue of ischemia–reperfusion injury mice, suggesting that Ori plays a protective role against oxidative stress and the inflammatory response." (PMID 37375489, 2023). "In addition, H2O2, MDA content, and the formation of conjugated dienes in the heart were increased in ischemia-reperfusion injury, while antioxidants such as SOD and catalase protected against these changes." (PMID 21789047, 2012).
kidney injury (4 papers, 2022 to 2025). Trauma to the kidney. "Nouri and Heidarian also highlighted the antioxidant role of NAC (100 mg/kg) via stimulation of CAT and SOD activity in their model of kidney injury induced by diclofenac." (PMID 37577725, 2023). "In our study, SKI increased the SOD, GSH-Px, and CAT activities and decreased the MDA content of adenine-induced kidney injury group, indicating that the protective effect of SKI may be related with its antioxidant activity." (PMID 35674582, 2022). "However, in IR-induced kidney injury in rats, the KD increased only the activity of the antioxidative enzymes GPX and SOD, but not CAT, while subcutaneous administration of BHB reversed the reduction in CAT mRNA expression in an SCI model." (PMID 36768899, 2023).
liver failure (4 papers, 2015 to 2023). A liver disease characterized by the liver losing or has lost all of its function. "This study demonstrated that proline supplementation in GalN-induced liver failure model significantly activated ROS-eliminating system such as catalase and glutathione system in the liver within 24 hours after GalN administration." (PMID 25984437, 2015).
lung adenocarcinoma (4 papers, 2010 to 2022). A carcinoma that arises from the lung and is characterized by the presence of malignant glandular epithelial cells. "The reduced proliferation of lung adenocarcinoma A549 cells by spider venom is may be associated with the increased of activity of catalase and MDA content and decreased expression of P38MAPK." (PMID 20959064, 2010). "In the human lung adenocarcinoma epithelial Calu-3 cell line, it was shown that treatment with the ErbB2-targeting antibody trastuzumab was associated with increased cellular ROS production, glutathione depletion, and decreased superoxide dismutase and catalase activities." (PMID 35372019, 2022). "The present study was designed to evaluate the association between antioxidant gene polymorphisms (SOD rs5746136 and SOD rs4880; CAT rs769218; OGG1 rs1052133; and TXN2 rs4821494) and EGFR-mutated lung adenocarcinoma." (PMID 32937815, 2020). "Spider venom can remarkably inhibite the proliferation of lung adenocarcinoma A549 cells, increased activity of catalase and MDA content, down-regulated expression of P38MAPK compared with the control group." (PMID 20959064, 2010).
malnutrition (4 papers, 2015 to 2025). Inadequate nutrition resulting from poor diet, malabsorption, or abnormal nutrient distribution. "In children and young adults, the total antioxidant capacity (TAC) and catalase levels were reduced in different types of malnutrition and recovered after dietary intake improvement and weight recovery." (PMID 34993223, 2021). "CAT is important when hydrogen peroxide is present at high concentrations and diseases of malnutrition have been shown to produce high levels of ROS." (PMID 25830944, 2015). "Malnutrition, the presence of ANFs, and insoluble fibers in RP may all cause the production of free radicals, which is mediated by antioxidant biomarkers such as TAC, CAT, and SOD84." (PMID 41272135, 2025).
mesothelioma (4 papers, 2014 to 2022). A usually malignant and aggressive neoplasm of the mesothelium which is often associated with exposure to asbestos. "Moreover, higher CAT expression in mesothelioma was associated with a better prognosis." (PMID 36467027, 2022). "On the other hand, numerous studies showed that cancer cells can exhibit high levels of ROS scavengers and antioxidants, such as catalase, which can also contribute to observed low baseline ROS formation in mesothelioma cell mitochondria." (PMID 32664372, 2020). "Expression of catalase in shPRX3 mesothelioma cells restores defects in cell proliferation but not sensitivity to TS." (PMID 26011724, 2015).
multiple myeloma (4 papers, 2018 to 2024). "In regression analysis, high MDA and NO levels, low GSH-Px, CAT, and SOD levels were identified as independent risk factors associated with multiple myeloma." (PMID 38540964, 2024). "In the present study, MDA and NO levels were found to be higher, and GSH-Px, SOD, and CAT levels were found to be lower in newly diagnosed multiple myeloma patients than in controls." (PMID 38540964, 2024). "In a prospective study, blood MDA levels were found to be higher, whereas SOD, CAT, glutathione, and glutathione-S-transferase activity levels were lower in multiple myeloma patients compared to control subjects." (PMID 38540964, 2024). "MDA (cut-off: >4.35, p < 0.001), GSH-Px (<59.8, p < 0.001), CAT (<67.2, p < 0.001), SOD (<21.2, p = 0.001), and NO (>38.5, p < 0.001) could significantly detect multiple myeloma." (PMID 38540964, 2024). "For all these reasons, we aimed to investigate whether various oxidant and antioxidant variables, including MDA, NO, GSH-Px, CAT, and SOD levels, can be used as reliable biomarkers for multiple myeloma and to assess which variables might be more sensitive in predicting multiple myeloma." (PMID 38540964, 2024). "Another study, although without a control group, showed that SOD, GSH-Px, and CAT levels, as well as NO and MDA levels, were significantly lower in multiple myeloma patients treated with vincristine, adriamycin, and dexamethasone." (PMID 38540964, 2024).
nephritis (4 papers, 2014 to 2024). Inflammation of renal tissue. "Our findings suggest that DEX downregulates cellular ROS generation, upregulates SOD and catalase activities, activates Nrf2/HO‐1 signal transduction, and reduces inflammation and apoptosis in nephritis." (PMID 38270316, 2024). "Similarly, SSa, as a free-radical scavenger, restores decreased SOD, CAT, and GPx activities in rats with nephritis." (PMID 34768813, 2021). "It has been suggested that the reduced activities of CAT and GPX in nephritis could be due to the inactivation of the enzymes by over-generation of H2O2." (PMID 24480247, 2014).
nephrotoxicity (4 papers, 2012 to 2023). Toxicity that causes injury to the kidney or damages its function. "However, serum levels of GPx, CAT, and SOD were significantly elevated in Cis + Infliximab-labeled PEG-coated SPIONs-loaded MSCs group compared to the Cis-induced nephrotoxicity rat model." (PMID 36425134, 2022). "However, serum levels of GPx, CAT and SOD were significantly elevated in Cis + MSCs, and Cis + Infliximab-labeled PEG-coated SPIONs-loaded MSCs (p < 0.05) compared to Cis-induced nephrotoxicity rat model (Table-6)." (PMID 36425134, 2022). "As shown in the results, there was a significant (p < 0.05) decrease in SOD, CAT, and GPx activities as well as a reduction in GSH levels of AlCl3-induced nephrotoxicity group with a significant (p < 0.05) increase in MDA levels of the AlCl3-induced nephrotoxicity compared to normal." (PMID 37649570, 2023).
Opportunistic infection (4 papers, 2017 to 2024). An infection that is caused by a pathogen that would generally not be able to cause an infection in a host with a normal immune system. "Non-fermenting oxidase and catalase-positive AGNBs detected in opportunistic infections are commonly identified as the family Pseudomonadaceae." (PMID 39935966, 2024). "Pseudomonas are Gram-negative, catalase-positive, nonfastidious organisms (thus having a wide distribution in nature) and are predominantly isolated due to nosocomial, opportunistic infections." (PMID 33149945, 2020).
peroxisomal disorders (4 papers, 2019 to 2025). "Under high metabolic demand or catalase (CAT) insufficiency, excess H2O2 may accumulate, contributing to oxidative liver injury and peroxisomal disorders." (PMID 40806653, 2025). "Finally, peroxisomal antioxidant defenses, enzymatic (catalase) and non-enzymatic (plasmalogen, DHA), can be compromised in peroxisomal disorders." (PMID 37974207, 2023).
Salmonella Infections (4 papers, 2023 to 2025). Infections with bacteria of the genus SALMONELLA. "Salmonella-infection in the group G2 resulted in significant (p < 0.05) decrease in the levels of CAT (52%), SOD (65%) and GR (60%) enzymes when compared to normal control." (PMID 37208771, 2023). "The activities of MDA, CAT, GSH-Px, and SOD in colon tissue after Salmonella infection were similar to those under hypoxia." (PMID 38037141, 2023). "However, the activity of catalase, which is the most abundant peroxisomal enzyme, was not altered after Salmonella infection." (PMID 39695325, 2025).
thalassemia (4 papers, 2015 to 2024). An inherited blood disorder characterized by a decreased synthesis of one of the polypeptide chains that form hemoglobin. "The study was designed to measure erythrocyte catalase activity (ECAT) in patients with IDA or BTT, to relate it with thalassemia mutation type (β0 or β+) and to compare it with normal subjects." (PMID 26527217, 2015).
uremia (4 papers, 2016 to 2023). A clinical syndrome associated with the retention of renal waste products or uremic toxins in the blood. "In a rat model of uremia, administration of B. clausii UBBC07 was associated with alleviation of oxidative response induced by acetaminophen, evidenced by increased levels of glutathione, superoxide dismutase, and catalase." (PMID 36838205, 2023). "The intestinal levels of MDA, SOD, CAT, and GSH-PX in the uremia group presented an increased trend over time, and these biomarker levels were higher than those in the control group at all the investigated time points." (PMID 27493661, 2016). "However, the intestinal levels of CAT of the uremia group were not significantly increased when compared with those of the control group at all the investigated time points (P > 0.05)." (PMID 27493661, 2016).
urinary tract infection (4 papers, 2014 to 2022). "These authors revealed that both SOD and CAT activities were significantly lower in T2DM subjects with urinary tract infection than healthy controls, suggesting that elevated OS caused enzyme consumption." (PMID 34336104, 2021). "Some enzymes which have been most extensively studied in the urine as markers for urinary tract infection are lactic dehydrogenase, glutamic oxaloacetic transaminase, alkaline phosphatase, β-glucuronidase, catalase, and superoxide dismutase." (PMID 24591758, 2014). "It is a catalase-negative, alpha-haemolytic gram-positive coccus that grows in clusters or tetrads and usually causes urinary tract infections." (PMID 36397095, 2022).
ZIKV infection (4 papers, 2017 to 2025). "Our results showed that ALIX, CD9 (exosomal biogenesis), SOD-1, and CAT (regulation of oxidative stress) had decreased protein expression levels during ZIKV infection, in contrast to the mock-infected cells." (PMID 40572291, 2025). "Unlike peroxisome biogenesis factors, levels of the peroxisomal matrix protein catalase were not affected by ZIKV infection." (PMID 31311201, 2019). "However, catalase knockdown reduced Dengue 4, but not Zika, infection prevalence (percent of infected midguts)." (PMID 28379952, 2017).
Zinc deficiency (4 papers, 2009 to 2025). A deficiency of the essential metal Zinc; an essential cofactor for many enzymes. "Zinc serves as a critical cofactor for numerous enzymes involved in antioxidant defense, including superoxide dismutase and catalase, whose dysfunction during zinc deficiency leads to increased oxidative stress and subsequent endothelial damage." (PMID 41158645, 2025). "In agreement, several enzymes involved in ROS detoxification were induced in F. pedrosoi under zinc deficiency: catalase, glutathione reductase, glutathione synthetase, glutathione-S-transferase, and Fe/Mn superoxide dismutase." (PMID 38392790, 2024). "Studies have revealed changes in SOD activity and other scavenging enzymes in epididymidis after zinc deficiency Hence, an increased CAT activity has been observed in caput and cauda epididymis of zinc deficient rats." (PMID 20177458, 2009). "The present study was designed to study the effects of zinc deficiency on catalase of testes and caput and cauda epididymidis." (PMID 20177458, 2009). "Thus, zinc deficiency increases catalase activity in testes and epididymis." (PMID 20177458, 2009).
acute liver failure (3 papers, 2020 to 2025). Rapid deterioration of liver function causing encephalopathy and coagulopathy. "The study on madecassoside found that it could ameliorate drug-induced acute liver failure by reducing inflammation (TNF-α ↓, IL-1β ↓, IL-6 ↓, iNOS ↓, COX-2 ↓) and oxidative stress (SOD ↑, CAT ↑, GPx ↑, Nrf2 ↑, HO-1 ↑)." (PMID 33013406, 2020).
acute pancreatitis (3 papers, 2009 to 2020). An acute inflammatory process that leads to necrosis of the pancreatic parenchyma. "The activities of several antioxidant enzymes, including glutathione peroxidase, SOD, and catalase, and levels of antioxidant vitamins decrease in patients with human acute pancreatitis." (PMID 29068376, 2017). "Previous studies have shown that DHA activates peroxisome proliferator-activated receptor-γ and induces catalase, which inhibits oxidative stress-mediated inflammatory signaling required for cytokine expression in experimental acute pancreatitis using cerulein." (PMID 29068376, 2017). "DHA-induced activation of PPAR-γ and catalase expression may be responsible for the anti-inflammatory effects of DHA in cerulein-induced acute pancreatitis." (PMID 29068376, 2017). "Plasma cAT expression was not considerably altered in patients with breast fibroadenomas, acute pancreatitis, chronic nephritis and cervicitis, and displayed slightly diminished levels in patients with chronic gastritis and acute appendicitis when compared to those of healthy control subjects." (PMID 19183436, 2009).